OAS2 (2'-5'-oligoadenylate synthetase 2)
Description:
Interferon-induced, dsRNA-activated antiviral enzyme which plays a critical role in cellular innate antiviral response. Activated by detection of double stranded RNA (dsRNA): catalyzes the formation of 2'-5'-oligoadenylates (2-5A) from polymerization of ATP which then bind to the inactive monomeric form of ribonuclease L (RNASEL) leading to its dimerization and subsequent activation. Activation of RNASEL leads to degradation of cellular as well as viral RNA, resulting in the inhibition of protein synthesis, thus terminating viral replication. Can mediate the antiviral effect via the classical RNASEL-dependent pathway or an alternative antiviral pathway independent of RNASEL. In addition, it may also play a role in other cellular processes such as apoptosis, cell growth, differentiation and gene regulation. May act as a negative regulator of lactation, stopping lactation in virally infected mammary gland lobules, thereby preventing transmission of viruses to neonates (By similarity). Non-infected lobules would not be affected, allowing efficient pup feeding during infection (By similarity).
Synonyms: AIAISD2
Tractability: PROTAC: ubiquitination databases record sites on it; its protein half-life has been measured.
Gene: Protein-coding gene on chromosome 12 (112,978,395 to 113,011,723, forward strand). Ensembl gene ENSG00000111335.
Subcellular location: Cytoplasm; Cytoplasm, perinuclear region; Golgi apparatus membrane
Subcellular location (Human Protein Atlas): Centrosome
Pathways (Reactome):
Immune System: Interferon alpha/beta signaling; Interferon gamma signaling; OAS antiviral response
Disease: RSV-host interactions
Gene Ontology:
Molecular function: 2'-5'-oligoadenylate synthetase activity; ATP binding; double-stranded RNA binding; protein binding; nucleotidyltransferase activity
Biological process: defense response to bacterium; interleukin-27-mediated signaling pathway; positive regulation of interferon-beta production; positive regulation of tumor necrosis factor production; antiviral innate immune response; defense response to virus; negative regulation of viral genome replication; nucleobase-containing compound metabolic process; regulation of lactation; response to virus; type I interferon-mediated signaling pathway; defense response
Cellular component: cytoplasm; Golgi membrane; membrane; perinuclear region of cytoplasm; cytosol; intracellular membrane-bounded organelle; nucleoplasm
Genetic constraint (gnomAD): Loss-of-function variants: 65 observed, 73.98 expected, observed/expected ratio (o/e) 0.88, 90% interval 0.72 to 1.08. The upper end of that interval is the gene's LOEUF score, 1.08, which puts it in group 4 of 6, group 1 being the genes least tolerant of losing a copy. Missense variants: 788 observed, 858.24 expected, observed/expected ratio (o/e) 0.92, 90% interval 0.87 to 0.97. Synonymous variants: 327 observed, 338.42 expected, observed/expected ratio (o/e) 0.97, 90% interval 0.88 to 1.06.
Homologues: Orthologues: chimpanzee OAS2 (98% identical), macaque OAS2 (92% identical), dog OAS2 (70% identical), pig OAS2 (68% identical), rabbit OAS2 (67% identical), mouse Oas2 (62% identical), rat Oas2 (60% identical), guinea pig OAS2 (53% identical). Paralogues in human: OAS3 (48% identical), OAS1 (27% identical), OASL (18% identical).
Diseases named in the same sentence as OAS2 in open-access papers:
OAS2 is named in the same sentence as 107 diseases in open-access papers, as found by Europe PMC text mining. Sharing a sentence is not in itself a finding about the gene and the disease. The quoted sentences say what the papers report.
viral infection (80 papers, 2008 to 2026). "OAS2 is known to encode a member of the 2-5A synthetase family, which comprises essential proteins involved in the innate immune responses to viral infection; it promotes viral RNA degradation and inhibition of viral replication." (PMID 33050948, 2020). "OAS2 gene, involved in the innate immune response to viral infection, was also found to be associated with the severity of liver disease in the HCV infected patients." (PMID 31660973, 2019). "The Oas2 gene encodes 2′,5’-oligoadenylate synthetase 2, which is a member of a family of essential proteins involved in the innate immune response to viral infection." (PMID 24755251, 2014). "OAS1 and OAS2 encode for two enzymes of the 2–5A synthetase family, involved in the innate immune response to viral infections." (PMID 23272139, 2012). "Under-expression of MX1, ISG15, RSAD2, IFIT1, and OAS2 may weaken the ability of the immune system to effectively counter viral infections, leaving the heart tissues susceptible to viral invasion and potentially contributing to MMVD progression." (PMID 38753730, 2024). "The proteins encoded by OAS2 are essential proteins involved in the innate immune response to viral infection; OAS2 is an interferon-regulated gene and its proteins are recurrently proposed in the literature as predictive biomarkers of interferon-beta treatment response." (PMID 32117605, 2020). "Upregulation of the Stat1-mediated response to the virus, interferon response, immune system activation, and ISGs, such as Rsad2, IFITM3, Cxcl9, Bst2, and Oas2, across all strains confirmed ongoing viral infection." (PMID 39875898, 2025). "Upregulation of the Stat1-mediated response to the virus, interferon response, immune system activation, and interferon-stimulated genes (ISGs; e.g., Rsad2, IFITM3, Cxcl9, Bst2, and Oas2) across all strains confirmed ongoing viral infection." (PMID 39875898, 2025). "OAS2 is an essential protein in the innate immune response against viral infection regulated by IFN." (PMID 37898694, 2023). "OAS2 is one of antiviral interferon-stimulated gene and plays an important role in resisting virus infection and innate immune response in COVID-19." (PMID 36162993, 2022). "IL-27 has been shown to play an important role in stimulating the transcription of cytosolic innate immune sensors, such as Mx1, Oas1, and Oas2, during viral infection." (PMID 36678402, 2022). "IRF1 transcriptionally induced by the phosphorylated STAT1 and stabilized by XAF1 further facilitates the induction of the IRF1 target genes such as DDX58, DDX60, MX1, and OAS2 during viral infection." (PMID 35972291, 2022). "IFIT1 and OAS2 were closely related to the activation of the autoimmune system due to virus infection." (PMID 35831878, 2022). "Other significantly upregulated genes include those from the oligoadenylate synthase (Oas) family (Oas1i, Oasl2, Oas2, Oas1a, Oas1g, Oas1f), which are stimulated by type 1 interferons in response to viral infections." (PMID 34436454, 2021). "We then quantified mRNA expression of IFN-β (type I IFN), IFN-λ (type III IFN), select ISGs (OAS2, IFIT1, IFIH1), and the neutrophil attracting chemokine IL-8 (CXCL8), which has been implicated in nasal inflammation during viral infection." (PMID 33811184, 2021). "For instance, OAS1 and OAS2 are responsible for the activation of ribonuclease L, which is part of the innate immune defense, during viral infection." (PMID 32155831, 2020). "2'‐5'‐oligoadenylate synthetase 2 (OAS2) gene, together with neighboring OAS1 and OAS3 gene, encodes enzymes participating in innate immunity response to viral infection." (PMID 30859738, 2019). "The most significant DMCs showed hypomethylation in 2′-5′-oligoadenylate synthetase 2(OAS2), which encodes a member of the IFN-inducible 2′-5′ synthetase family, involved in the innate immune response to viral infections." (PMID 34968227, 2019).
viral infection (continued). "OAS2 and OAS3 encode a members of the 2–5A synthetase family, essential proteins involved in the innate immune response to viral infection." (PMID 29642892, 2018). "The second gene, OAS2, is a member of the 2–5A synthetase family which is involved in the immune response to viral infections." (PMID 28443095, 2017). "As OAS2 is involved in the innate immune response to viral infection we performed cell line experiments to study gene expression and DNA methylation in response to innate immune triggers." (PMID 27572959, 2016). "MX1 and OAS2 are antiviral proteins that play an important role in the type I interferon-mediated response against a broad range of viral infections." (PMID 26419927, 2015). "Several interferon-inducible genes involved in immune response to viral infection (including OAS2, ISG15, STAT1, and ADAR) were identified as “drivers” in this sub-network based on the ARACNE and key driver analysis." (PMID 25868721, 2015). "The authors did, however, detect DMRs in another interferon-induced gene, ‘interferon alpha inducible protein 27’ (IFI27), as well as in ‘2′-5′-oligoadenylate synthetase 2’ (OAS2) which is a member of the 2–5 A synthetase family known to be involved in the innate immune response to viral infection." (PMID 35798818, 2022). "In addition, MVP was down-regulated and OAS2 was up-regulated in the lipid rafts of infected HIBCPP cells, both implicated in innate immune response following viral infection." (PMID 33321840, 2020). "Human OAS1 and OAS2 have proved to be ineffective for activation of RNaseL upon virus infection." (PMID 30587119, 2018). "The fact that OAS2 expression was higher at 72 h than 24 h could reflect the time required for induction of IFN expression by the viral infection and/or modulation of the IFN response by adenoviral genes." (PMID 28107341, 2017). "Finally, OAS2 (2'-5'-oligoadenylate synthetase) is an interferon-induced molecule that is involved in the innate immune response towards viral infection." (PMID 24013589, 2013). "According to related studies, the expression level of OAS1 in anti-viral infection is higher than that of OAS2 and OAS3, and there is a high correlation between the expression of OAS1 and the other three OAS genes, which may indicate the important role of OAS1." (PMID 36162993, 2022). "Thus, the association of IRF-1, IFI-44, Mx1, OAS2, and HSH2D with HLA-DR could suggest a possible relationship between viral infection and HLA-DR expression." (PMID 30374345, 2018). "Meanwhile, the transcriptional levels of interferon-stimulated genes (ISGs) such as ISG15, ISG20, OAS1, OAS2, MX1, and MX2 were significantly up-regulated, and these ISGs play a crucial role in resisting viral infection." (PMID 41153955, 2025). "The induction of OAS1, OAS2, and OASL, which, as main sensors for viral infections, explains the induction of numerous interferon-induced proteins (e.g., IFIT1, IFIT2, IFI44, MX1, MX2)." (PMID 39062793, 2024). "Previous studies have identified that following viral infection, type I IFN signaling induces the production of the OAS family consisting of OAS1, OAS2, OAS3, and OAS-like (OASL) protein." (PMID 38650851, 2024). "For example, upregulated genes OASL, OAS1, OAS2, and OAS3 belong to the OAS family, a group of antiviral enzymes induced by type I IFNs, which can locate and bind viral dsRNA after viral infection." (PMID 36655136, 2023). "These pathways are closely related to the ability to respond to viral infections, and many downstream genes of JAK/STAT1/2-ISGs signaling, including Oas2, Ifit1, and MX1, which have anti-viral activities." (PMID 36599833, 2023). "SARS-CoV-2-infected Calu-3 cells exhibited upregulation of genes involved in innate immune response to viral infections such as IFIT2, OAS2, or IFNB1, similar to the responses elicited by the SARS-CoV-1 virus." (PMID 35464437, 2022).
viral infection (continued). "Especially, many ISGs were modified with ubiquitin during viral infections such as MX1, MX2, OAS2, ISG15, and ISG20, which has rarely been reported before." (PMID 36071039, 2022). "Downregulation of lincRNA‐EPS during viral infection or genetic knockout of lincRNA‐EPS facilitates PKR‐STAT1 signaling axis induced antiviral genes expression, such as Mx1, Oas2, Ifit2, and Irf7." (PMID 35312140, 2022). "ISGs products, including OAS1, OAS2, MX1, ADAR, and EIF2AK2, are major players in innate immune defence against viral infection." (PMID 36016774, 2022). "In the current report, we found that IAV infection increases MAGI1 expression and enhances virus infection by inhibiting various anti-viral responses including STATs and IRF3 activation and induction of MX1 and OAS2." (PMID 36082118, 2022). "In our data, the enriched pathways were related to viral infections such as influenza A (MX1, OAS1, OAS2, OAS3, RSAD2, STAT1) and measles (MX1, OAS1, OAS2, OAS3, STAT1)." (PMID 35464437, 2022). "SARS-CoV-2 infection of Calu-3 cells, as expected from similar results for SARS-CoV infections, led to induction of a range of genes known to respond to viral infections, such as IFIT2, OAS2, or IFNB1." (PMID 33585804, 2021). "The top genes in the individual LIMMA analyses that were differentially expressed in peripheral blood samples of patients hospitalized with viral infection vs. bacterial (baseline in the model) infection were ISG15, TIMM10, IFI27, IFI44L and OAS2." (PMID 34593881, 2021). "Previous work has identified that following viral infection, type I IFN signaling induces the production of the 2′-5′-oligoadenylate synthetase (OAS) family, which include OAS1, OAS2, OAS3, and OAS-like (OASL) protein." (PMID 28580319, 2017). "Driver genes of this sub-network (OAS2, ISG15, STAT1, and ADAR) are involved in immune response to viral infections, and expression of these genes is inducible by interferon." (PMID 25868721, 2015). "Indeed, many interferon‐related genes upregulated during viral infection in rats were found to be downregulated by PTS in this study (e.g., Oas1a, Oas2, Irf7, Ifi27, Lgals3 bp)." (PMID 39562169, 2024). "The increase in OAS2 and MX1 once again underscores a shared antiviral strategy across different viral infections, and ISG15 (interferon-stimulated gene 15) points to a broader modulation of the immune response, given its role in protein ubiquitination related to antiviral defense." (PMID 38655085, 2024). "Individually, IFNβ pretreatment or OAS2 re-expression could specifically protect cells expressing MYC and AKT oncogenes from viral infection, suggesting oncogene-driven suppression of antiviral defense pathways increases viral susceptibility." (PMID 35594991, 2022). "However, our results show that viral infection or genetic knockout of lincRNA‐EPS facilitates PKR‐STAT1 signaling axis induced antiviral genes such as Mx1, Oas2, Ifit2, and Irf7, while inhibits phosphorylation of TBK1 and IRF3, as well as the IFN‐β induction." (PMID 35312140, 2022). "OAS2 belongs to the human 2′-5′-oligoadenylate synthetase family, which participates in nonspecific immunity during viral infection through interferon induction and degrades viral RNA." (PMID 34603483, 2021). "A subset of genes including OAS1, OAS2, EFNB2, and CKS1B involved in the immune response to viral infection showed a higher expression level and H3K4me3 enrichment in PEDV-infected samples, suggesting the role of H3K4me3 deposition in promoting their expression." (PMID 31382472, 2019). "Induction of OAS proteins by IFN and viral replication leads to synthesis of 2’5’ oligoadenylates which activate RNase L. OASs (OAS1, OAS2, OAS3) synthesize 2’-5’ oligoadenylates and activate RNase L leading to degradation of viral and cellular RNAs, thereby restricting viral infections." (PMID 30779786, 2019).
viral infection (continued). "The potential role of OAS3 in the recognition of CpG- and UpA-high mutants is consistent with its demonstrated preferential role in mediating RNAseL responses to a wide range of virus infections, and the frequent inactivity of OAS1 (and OAS2) in antiviral defence." (PMID 31276592, 2019). "MX1, MX2, and OAS family members OAS1, OAS2, OAS3 mediate resistance to virus infection." (PMID 18648529, 2008). "Finally, the overexpression of MX1, a well-characterized biomarker of viral infection; IFIT1, one of the top upregulated genes; and OAS1, OAS2 and OAS3, genes with a molecular function, 2-5-oligoadenylate synthase activity, identified as enriched in the DGE analyses, was confirmed by RT-qPCR." (PMID 42194954, 2026). "Various studies have demonstrated that ISG15, 2′-5′ oligoadenylate synthase (OAS2), double-stranded RNA protein kinase R (PKR), interferon-induced transmembrane protein 1 (IFITM1), and nitric oxide synthase (NOS) play a crucial role in inhibiting viral infections." (PMID 37256060, 2023). "A variety of genes such as OAS2, PARP9, OASL, IFIT2, IFI3, CCL8, CXCL10, etc., were highly upregulated and correlated with high viral load, suggesting that innate immune response genes were activated in a viral load dose response manner to control the viral infection." (PMID 37333115, 2023). "To investigate whether the antiviral effect of C11orf83 is through OASs-RNase L system, we examined the expression of OAS family four members (OAS1, OAS2, OAS3, and OASL) at the mRNA level in HEK293 cells that only overexpressed C11orf83 but no viral infection." (PMID 28418037, 2017).